IL1A (interleukin 1 alpha)
Diseases named in the same sentence as IL1A in open-access papers (continued):
Sharing a sentence is not in itself a finding about the gene and the disease.
anthrax (1 paper, 2015). "Elevated transcription of TNF-α, IL-1α, IL-1β, IL-4, IL-6, CCL5, CXCL2 and KC have been observed in both murine anthrax challenge models and in vitro macrophages and monocytic cell lines exposed to anthrax antigens." (PMID 26075052, 2015).
aortitis (1 paper, 2019). Inflammation of the aorta. "It was reported that the development of aortitis was diminished in Il1r1−/−Il1rn−/− mice and Tnfa−/−Il1rn−/− mice, whereas it was normal in Il6−/−Il1rn−/− mice, indicating that IL-1α and/or IL-1β, and TNF are crucial for development of aortitis in Il1rn−/− mice." (PMID 31745167, 2019).
appendicitis (1 paper, 2024). Acute inflammation of the vermiform appendix. "The aim of the present study was to evaluate how the Th1 and Th17-associated cytokines IL-1α, IL-1β, IL-2, IL-6, IL-10, IL-17A and tumor necrosis factor beta (TNF-β) are associated with the risk of complicated appendicitis in children." (PMID 38409170, 2024). "This prospective cohort study aimed to evaluate the association between serum concentrations of the Th1-associated cytokines interleukin (IL)-1α, IL-1β, IL-2, IL-6, IL-10, IL-17A and tumor necrosis factor beta (TNF-β) and the risk of complicated appendicitis in children." (PMID 38409170, 2024). "High serum concentrations of IL-6 were associated with an increased risk of complicated appendicitis in children, whereas serum concentrations of IL-1α, IL-1β, IL-2, IL-10, IL-17A and TNF-β were not." (PMID 38409170, 2024).
arterial disease (1 paper, 2022). "Concomitant arterial disease in mixed venous-arterial ulcers did not influence the levels of EGF, FGF-2, IL-1α, IL-1β, IL-6, PDGF, TGF-β1 and TNF-α in one study." (PMID 35742965, 2022).
arteritis (1 paper, 2022). An inflammatory process affecting an artery. "On the other hand, IL-1α/β-KO mice did not develop CAWS-induced arteritis 39, confirming the direct pathogenic role of IL-1β in CAWS-induced arteritis." (PMID 35173530, 2022).
astroglioma (1 paper, 2023). "In this work, we induced the generation of A1-like reactive astrocytes after the co-treatment of U251 human astroglioma cells with a cocktail of the cytokines TNF-α, IL1-α and C1q." (PMID 37513235, 2023).
autoimmune uveitis (1 paper, 2015). An autoimmune form of uveitis (disease). "We found that bortezomib treatment in EAU mice could suppress not only TNF-α but also many other inflammatory mediators such as IL-1α, IL-1β, IL-12, IL-17, and MCP-1 in retinas so the autoimmune uveitis could be more effectively suppressed with bortezomib than with TNF-α antagonist etanercept." (PMID 25653480, 2015).
B-cell lymphoblastic leukemia (1 paper, 2024). "In studies, patients with B-cell lymphoblastic leukemia following CAR-T cell therapy presented elevated levels of IL-1α, IL-2, IL-3, IL-5, IL-6, IL-8 IL-10, IL-15, IFN- γ, procalcitonin, CRP, G-CSF, GM-CSF, and MCP-1, and their levels were linked to the severity of neurotoxicity." (PMID 39409959, 2024).
bacterial pneumonia (1 paper, 2021). Acute infection of the lung parenchyma caused by bacteria (e.g., Streptococcus pneumoniae, Haemophilus influenzae, Chlamydia pneumoniae, Mycoplasma pneumoniae, and Legionella pneumophila). "Although both virus-infected groups were asymptomatic, almost equally high cytokine levels were detected locally and systemically as compared to single bacterial pneumonia, with the exception of IL-1α." (PMID 34663857, 2021).
benign prostatic hyperplasia (1 paper, 2021). A non-cancerous nodular enlargement of the prostate gland. "Investigations demonstrated that in PC and benign prostatic hyperplasia (BPH), the expression of IL-1α and IL-1RI in epithelial cells was up-regulated and associated with cell proliferation and high prostate-specific antigen levels." (PMID 34868907, 2021).
bile duct cancer (1 paper, 2023). "Importantly, human pancreatic, stomach, brain, and bile duct cancer all have overexpression of both IL-1α and LIF relative to normal tissue while having only minor changes in G-CSF." (PMID 37134077, 2023).
bladder tumor (1 paper, 2022). "Indeed, we observed upregulation of HIF-1α in human bladder tumor samples, together with VEGF (angiogenesis) and IL-1α and IL-1β (inflammation), which are indicative of poor prognosis in cancer and aggressiveness." (PMID 36233054, 2022).
blood pressure (1 paper, 2017). "Elevated blood pressure accelerates atherogenesis while angiotensin-II may independently promote vascular inflammation by increasing oxidative stress in vessel walls ICAM1 (inter-cellular adhesion molecule-1) was also up-regulated by IL-1α in other studies." (PMID 28323859, 2017).
bone tumours (1 paper, 2016). "It is possible that inhibition of IL-1A, as well as downstream effects on other cytokines including TNF alpha, contribute to the reduced of growth of both subcutaneous and bone tumours following administration of anakinra." (PMID 27765923, 2016).
brain tumors (1 paper, 2013). "Additionally, ACA increased the protein expression levels of the pro-survival signaling cytokines, IL-6 and IL-1α, established cell protectors and survival molecules in brain tumors." (PMID 23833677, 2013).
bronchiolitis (1 paper, 2016). Inflammation of the bronchioles characterized by swelling of the bronchioles and mucus accumulation. "KC induces chemotaxis in inflammatory granulocytes and is believed to play a role in the pathogenesis of bronchiolitis, while IL-1α has been shown to increase vascular permeability." (PMID 26844553, 2016).
bubonic plague (1 paper, 2012). A plague in which the bacteria have infected the lymphatic system. "A recent study of the systemic phase of bubonic plague due to fully virulent Y. pestis CO92 showed high levels of the PMN maturation factor G-CSF, chemokines CXCL1 and CCL2, as well as cytokines IL-6 and Il-1α in plasma." (PMID 23248776, 2012).
bullous keratopathy (1 paper, 2023). "It has already been proven that the levels of some proinflammatory cytokines, such as interleukin (IL)-1a, IL-6 IL-8, IL-17a, TNF-alpha, and IFN-c, were higher in the aqueous humor of eyes with bullous keratopathy and a low density of ECs." (PMID 36968840, 2023).
burn (1 paper, 2012). A traumatic injury involving interruption of tissue cohesiveness that results from exposure to caustic chemicals, extreme heat, extreme cold or excessive radiation. "Increased levels of IL-1α, IL-2, IL-4, IL-10, IFN-γ and TNFα could be detected in culture media of burn injury skin cultures." (PMID 22359539, 2012).
cerebral artery occlusion (1 paper, 2023). "In animal models, IL-1a was found to be up-regulated after acute middle cerebral artery occlusion, inducing migration, proliferation and angiogenesis in brain endothelial cells." (PMID 37292135, 2023).
cerebral infarction (1 paper, 2016). An ischemic condition of the brain, producing a persistent focal neurological deficit in the area of distribution of the cerebral arteries. "In conclusions, our results suggested that polymorphisms of IL-1α −899C/T, IL-6 −572C/G and IL-18 −607C/A were positive correlated with increased the risk of cerebral infarction." (PMID 27679860, 2016). "For IL-1α −899C/T polymorphism, 9 articles included 2933 cerebral infarction patients and 3554 controls." (PMID 27679860, 2016). "In conclusion, IL-1α −899C/T, IL-6 −572C/G and IL-18 −607C/A might be risk factors for cerebral infarction development." (PMID 27679860, 2016). "Our results found that polymorphisms of IL-1α −899C/T and IL-18 −607C/A (under all the genetic models), and IL-6 −572C/G (under the allelic model, heterogeneity model and dominant model) were associated with increased the risk of cerebral infarction." (PMID 27679860, 2016). "Our result showed that IL-1α −899C/T and IL-18 −607C/A (under all the genetic models), and IL-6 −572C/G (under the allelic model, heterogeneity model and dominant model) were associated with increased the risk of cerebral infarction (P<0.05)." (PMID 27679860, 2016).
cervical (1 paper, 2020). "IL1A plays a pivotal role in cervical carcinogenesis and progression." (PMID 32047552, 2020).
cholangitis (1 paper, 2018). An acute or chronic inflammatory process affecting the biliary tract. "When we neutralized IL-15, levels of IL-1α were restored and this was associated with attenuated cholangitis." (PMID 29449577, 2018).
chronic cervicitis (1 paper, 2024). Chronic inflammation of the cervix. "We used a set of patient-derived precancerous (n = 32) and noncancerous (chronic cervicitis; n = 10) tissue samples to investigate the gene expression of several OIS (LMNB1, CDKN2A, CDKN2B, and CDKN1A), and SASP (IL1A, CCL2, TGFB1, CXCL8, and MMP9) biomarkers using qRT-PCR." (PMID 39727946, 2024).
chronic GVHD (1 paper, 2025). "We found no significant SNP IL-1α rs1800587 (C > T) associations for chronic GVHD, RR, TRM, EFS, and OS." (PMID 41291248, 2025). "Some studies have described patients who did not have the TT allele at IL-1α rs1800587 having a higher rate of chronic GVHD." (PMID 41291248, 2025). "We also investigated the incidence of chronic GVHD, OS, EFS, RR, and TRM, as well as the possible influence of the SNPs of IL-1α rs1800587, IL-1β rs1143627, and IL-1β rs16944." (PMID 41291248, 2025).
conjunctivitis (1 paper, 2022). Inflammation of the conjunctiva of the eye. "The IL-1α mRNA expression levels were largely unrelated to the severity of conjunctivitis." (PMID 36184619, 2022).
constrictive pericarditis (1 paper, 2024). A heart disorder in which the pericardial sac becomes thickened and fibrotic, tightening the myocardium and impeding the normal myocardial function. "Since IL-1α is primarily membrane-bound, its inflammatory effects are localized in the pericardium, causing inflammation and occasionally fibrosis, which occasionally may progress to constrictive pericarditis." (PMID 38541631, 2024).
crescentic glomerulonephritis (1 paper, 2024). A histopathologic term for a pattern of diseases characterized by extensive crescent formation in the glomeruli; patients present clinically with rapid deterioration of renal function, and possible progression to end-stage renal failure within weeks or months. "In an in vitro culture of glomerular cells in patients with rapidly progressing crescentic glomerulonephritis, a gradual increase in IL1A production over time has been found." (PMID 39108259, 2024).
demyelination (1 paper, 2022). "Previous studies demonstrated that a substantial number of A1 astrocytes were activated in CPZ-induced demyelination lesions, and the A1 phenotype was mainly triggered by C1q, TNF-α, and IL-1α derived from microglia." (PMID 36092158, 2022).
diabetic retinopathy (1 paper, 2022). "Furthermore, in mice with STZ-induced diabetic retinopathy, intravitreal injection of the MC5R peptidomimetic agonist PG-901 attenuated, while MC5R antagonist PG20N augmented, retinal release of various inflammatory cytokines, such as IL-1α, IL-1β, IL-6, MIP-1α, MIP-2α, and MIP-3α." (PMID 35721571, 2022).
dystocia (1 paper, 2014). Slow or difficult obstetric labor or childbirth. "In the present study, dystocia was associated with a greater localized inflammatory response, as characterized by the accumulation of more IL-1β, IL-8 and IL-1α in vaginal mucus 3 weeks postpartum compared with healthy animals." (PMID 25395028, 2014). "Animals that suffered dystocia had increased concentrations of inflammatory mediators IL-8, IL-1β and IL-1α in vaginal mucus 3 weeks postpartum, but they also had more bacteria than normal animals." (PMID 25395028, 2014). "As vaginal mucus accumulated IL-1α in animals with dystocia and infection, and the only in vitro responses to potential DAMPs were to IL-1α, the production of IL-1α was explored further in endometrial cells." (PMID 25395028, 2014). "The accumulation of IL-1α in the vaginal mucus of animals with dystocia and infection 3 and 5 weeks but not 1 week postpartum was intriguing because if IL-1α was a DAMP, one might expect the highest concentration soon after the trauma of dystocia." (PMID 25395028, 2014).
ectodermal dysplasia (1 paper, 2022). "In HC rat lungs at P14, the number of ectodermal dysplasia (ED)-1- and TUNEL-positive cells and level of inflammatory cytokines such as interleukin (IL)-1α, IL-1β, IL-6, and TNF-α were significantly increased." (PMID 35743045, 2022).
endometrial cancer (1 paper, 2022). Primary or metastatic malignant neoplasm involving the endometrium (mucous membrane that lines the endometrial cavity). "In detail, three large case studies demonstrated a relationship between the circulating levels of TNF-α, IL-6, IL-1α, and C-reactive protein (CRP) and elevated risk of endometrial cancer." (PMID 35053431, 2022).
epididymitis (1 paper, 2023). Inflammation of the epididymis. "In the vivo experiments, levels of the proinflammatory cytokines IL-1α, IL-6, IL-17A, TNF-α, IL-1β, MCP-1, and GM-CSF, mRNA for MyD88 related genes, and the percentages of monocyte-derived DCs (Mo-DCs) were significantly elevated in mice with epididymitis." (PMID 37175545, 2023).
Epstein-Barr virus infection (1 paper, 2020). An infection that is caused by Epstein-Barr virus. "For example, Epstein-Barr virus infection in B or T cells induced TNF-α, but not IL-1α." (PMID 33072000, 2020).
erythroleukemia (1 paper, 2022). Acute erythroid leukemia characterised by the presence of at least 50% erythroid precursors and at least 20% myeloblasts in the bone marrow. "In addition, IL1-α, Il-12 and VEGF, that have been shown to support the growth of murine erythroleukemia cells in the spleen, were also upregulated in the spleen in our study." (PMID 36163264, 2022).
Ewing sarcoma (1 paper, 2007). A small round cell tumor that lacks morphologic, immunohistochemical, and electron microscopic evidence of neuroectodermal differentiation. "Cultures of Ewing's sarcoma TAMs incubated on dentine slices for 21 days in the presence of M-CSF/RANKL or TNF-α/IL-1α showed a functional evidence of osteoclast differentiation with the formation of several areas of lacunar resorption on all dentine slices." (PMID 17533390, 2007).
Fabry disease (1 paper, 2024). Fabry disease (FD) is a progressive, inherited, multisystemic lysosomal storage disease characterized by specific neurological, cutaneous, renal, cardiovascular, cochleo-vestibular and cerebrovascular manifestations. "Patients with Fabry disease also demonstrate an increase in T cell subsets and increased circulatory levels of pro-inflammatory cytokines, such as TNFα, IFNγ, IL1α, IL1β, IL6, and IL17." (PMID 39596318, 2024).
febrile seizures (1 paper, 2012). "Two proteins identified in this study have been described in human genetic studies before: single nucleotide polymorphisms (SNPs) present in IL-1α and IL-10 genes are associated with TLE and febrile seizures respectively." (PMID 22935090, 2012).
Follicular Cyst (1 paper, 2023). Cyst due to the occlusion of the duct of a follicle or small gland. "FGF7 regulated the PPAR signaling pathway (FABP5 and SCD) and the MAPK signaling pathway (FGF1, FGFR2, IL1A, TGFB1, and CSF1) and pathways in cancer (IL7, CD44, SMAD2, and MMP2) may be involved in the formation of follicular cysts." (PMID 38274662, 2023).
food allergy (1 paper, 2023). Gastrointestinal disturbances, skin eruptions, or shock due to allergic reactions to allergens in food. "To investigate the role of IL-1α in food allergies mediated by δ-toxin present on the steady-state skin, we pretreated the mice with anti-IL-1α Ab or control Ab." (PMID 37275864, 2023). "Even without tape stripping, δ-toxin present on skin enhances epicutaneous sensitization to food allergen in an IL-1α-dependent manner, thereby promoting the development of food allergy." (PMID 37275864, 2023). "Therefore, targeting IL-1α may be an appropriate strategy to prevent the development of food allergy in individuals whose skins are colonized by δ-toxin-producing S. aureus." (PMID 37275864, 2023).
fucosidosis (1 paper, 2015). "Additional inflammatory genes including major histocompability class II, chemokine C-C motif receptor-1 and 5, cathepsin S and IL1A are upregulated in preclinical fucosidosis frontal cortex and may also be suitable candidates for monitoring responses to therapy in the future." (PMID 26537923, 2015).
gallstones (1 paper, 2021). Solid crystalline precipitates in the biliary tract, usually formed in the gallbladder, resulting in the condition of cholelithiasis. "IL-1α is expressed in basal level in epithelium during normal physiological state, and even more during inflammation; thus, its increased expression in connective tissues could also probably be potentiated by epithelial necrosis, caused by gallstone induced injury." (PMID 34449702, 2021).
gastric tumors (1 paper, 2015). "The current dogma supports the view that IL-1β promotes enrichment of MDSCs in the stomach thus balancing the alarmin activity of IL-1α, and can lead to gastric tumour formation." (PMID 25528766, 2015).
Gingival bleeding (1 paper, 2021). Hemorrhage affecting the gingiva. "The levels of IL-1α, IL-8, and IL-4 were higher in the gingival bleeding-high group than those in the gingival bleeding-low group." (PMID 34199256, 2021).
granulocytosis (1 paper, 2011). "Recent studies indicate the important role of IL-1α released from dead cells for the induction of granulocytosis." (PMID 21760797, 2011).
Graves disease (1 paper, 2018). Graves' disease is an autoimmune disorder that leads to overactivity of the thyroid gland (hyperthyroidism).It is caused by an abnormal immune system response that causes the thyroid gland to produce too much thyroid hormones. "Based on the available data, C/T genotype of the rs1800587 polymorphism within IL1A gene may be associated with an increased Graves’ disease risk." (PMID 29879187, 2018). "Taken together, based on published articles in databases, our meta-analysis suggested that the rs1800587 polymorphism, rather than rs17561, within the IL1A gene, may be a genetic risk factor for Graves’ disease." (PMID 29879187, 2018).
H1N1 influenza (1 paper, 2013). "In this study, we investigated the relationship between single-nucleotide polymorphisms (SNPs) of Interleukin-1A (IL-1A) and Interleukin-1B (IL-1B) and the susceptibility to 2009 pandemic A/H1N1 influenza (A(H1N1)pdm09)." (PMID 23927441, 2013).
Hashimoto thyroiditis (1 paper, 2021). An autoimmune disorder caused by the production of autoantibodies against thyroid tissue. "ROS were detected by the 2′,7′-dichlorodihydrofluorescein diacetate (CM-H2DCFDA) method in human thyrocytes treated with IL-1α and IFNγ to mimic Hashimoto’s thyroiditis (HT) and compared to non-treated cells." (PMID 33916948, 2021).
hemarthrosis (1 paper, 2020). Bleeding into the joints. "Indeed, when activated by erythrocyte phagocytosis, monocytes and macrophages were reported to produce IL‐1β and TNF‐α in the joint after hemarthrosis, which could explain the control of FLS expression by a negative feedback pathway of IL‐1α but this hypothesis needs to be confirmed." (PMID 33159500, 2020).
histiocytic lymphoma (1 paper, 2014). "An anti-calpain I antibody blocked Ca2+-dependent processing of pro-IL-1α in lysates U937 histiocytic lymphoma cells." (PMID 24790078, 2014).
Hodgkins lymphoma (1 paper, 2025). A heterogeneous group of malignant lymphoid neoplasms of B-cell origin characterized histologically by the presence of Hodgkin and Reed-Sternberg (HRS) cells in the vast majority of cases. "Cytokines involved in EMH, such as IL-1α and leukemia inhibitory factor, may have been secreted by the Hodgkin lymphoma cells." (PMID 39974298, 2025).